SUCNR1 (succinate receptor 1)
Diseases named in the same sentence as SUCNR1 in open-access papers (continued):
Sharing a sentence is not in itself a finding about the gene and the disease.
Hyperglycemia (15 papers, 2011 to 2026). An increased concentration of glucose in the blood. "The upregulation of SUCNR1 associated with hyperglycemia differs, however, from the downregulation reported for GLP-1R in conditions associated with high glucose." (PMID 38713514, 2024). "Our study provides insights into the long-observed yet previously unclear mechanism by which hyperglycemia accelerates vitiligo progression and highlights SUCNR1 as a potential therapeutic target." (PMID 42294897, 2026). "Our findings identify the succinate/SUCNR1 axis as an amplifying route for insulin secretion in response to hyperglycemia." (PMID 38713514, 2024). "SUCNR1, expressed in β cells and upregulated in hyperglycemia, is essential for maintaining insulin secretion in diet-induced insulin resistance and prediabetic states." (PMID 38713514, 2024). "Remarkably, Sucnr1-βKO mice showed an overall higher diet-induced hyperglycemia than control mice, which was particularly significant in random-fed conditions." (PMID 38713514, 2024). "A recent study showed that Sucnr1−/− mice have increased body weight, with concurrent hyperglycaemia and impaired glucose tolerance, in contrast to our observations." (PMID 28382382, 2017). "Thus, hyperglycemia aggravates vitiligo through succinate/SUCNR1 axis-regulated CD8+ T cell hyperactivation." (PMID 42294897, 2026). "Mechanistically, succinate-mediated SUCNR1 activation has been connected to angiogenesis, wherein hyperglycaemia-induced increases in succinate levels activate SUCNR1, stimulating VEGF release and promoting endothelial cell proliferation and migration in vitro." (PMID 38182909, 2024). "We next explored a potential link between hyperglycemia and the succinate/SUCNR1 axis in β cells." (PMID 38713514, 2024). "Effectiveness of these novel drugs may likely be extended to unresectable or metastatic SDH-deficient renal cell carcinomas, gastrointestinal stroma tumors, thyroid, and pancreatic neuroendocrine tumors, or other conditions exhibiting disturbed SUCNR1-signaling due to hypoxia or hyperglycemia." (PMID 33776908, 2021). "In addition, the SUCNR1 may also have a role for immunity, hyperglycemia, retinal neovascularization, ischemic liver injury and hematopoiesis as reviewed recently." (PMID 21967230, 2011).
Hypertension (14 papers, 2017 to 2025). The presence of chronic increased pressure in the systemic arterial system. "The succinate receptor (SUCNR1) hasemerged as a potentialtargetfor the treatment of various metabolic and inflammatory diseases,including hypertension, inflammatory bowel disease, and rheumatoidarthritis." (PMID 37318348, 2023). "A SUCNR1 polymorphism (rs73168929), affecting the 3′ untranslated region (UTR) of the gene, which is an important zone involved in miRNA binding, has recently been linked to type 2 diabetes and hypertension susceptibility in a Chinese population." (PMID 38182909, 2024). "The multifaceted receptor, SUCNR1, has been attributed to kidney physiopathology via stimulation of the local and systemic renin–angiotensin system, development of metabolic syndrome, and hypertension." (PMID 36551549, 2022). "Thus, changes in SUCNR1 expression due to alterations in miRNA binding may serve as a predictive biomarker of type 2 diabetes and hypertension, although further research is needed." (PMID 38182909, 2024). "As already discussed, the succinate receptor SUCNR1/GPR91 is known to play a role in several diseases including diabetic retinopathy, diabetic renal disease, hypertension, atherothrombosis, neuroinflammation, rheumatoid arthritis, and metabolic dysfunctions." (PMID 31333642, 2019). "Once outside the cell, it can bind to the succinate receptor SUCNR1/GPR91, a G-protein–coupled cell surface sensor for extracellular succinate expressed in many cell types, that is known to be activated in diabetic retinopathy, diabetic renal disease, hypertension, and atherothrombosis." (PMID 31333642, 2019).
rheumatoid arthritis (12 papers, 2019 to 2026). A chronic, systemic autoimmune disorder characterized by inflammation in the synovial membranes and articular surfaces. "In rheumatoid-arthritis (RA) patients, extracellular succinate that accumulates in synovial fluid engages SUCNR1 to direct DC migration to lymph nodes, leading to an increased frequency of Th17 cells." (PMID 41000375, 2025). "While the succinate-SUCNR1 interplay has been proposed as a molecular mechanism in rheumatoid arthritis and intestinal inflammation, our data also imply a role for this pathway also in EMs formation." (PMID 38291428, 2024). "In inflammatory disorders, such as rheumatoid arthritis, macrophage-released succinate upregulates SUCNR-1 expression on M1 macrophages and stimulates IL-1β production via SUCNR-1 to exacerbate arthritis." (PMID 37446354, 2023). "IL-1β can also be produced independent of HIF-1α through the inflammatory release of succinate by macrophages which activates succinate receptor 1 (SUCNR1)/G-protein coupled receptor 91 (GPR91) and enhances the adverse effects of rheumatoid arthritis." (PMID 33153035, 2020). "As exhibited, succinate has a role in the inflammatory response of cells, and further research can provide therapeutic options as seen with SUCNR1/GPR91 inhibitors for rheumatoid arthritis." (PMID 33153035, 2020). "Mice deficient in the G-protein coupled receptor, succinate receptor 1 (SUCNR1; previously known as GPR91) demonstrated impaired IL-1β production with either LPS activation or in a model of rheumatoid arthritis." (PMID 35792320, 2022).
atherosclerosis (8 papers, 2015 to 2025). A disease characterized by the build-up of fatty material and calcium deposition in the arterial wall resulting in partial or complete occlusion of the arterial lumen. "Sucnr1 may act as a novel target for cutting off succinate signal transduction to prevent the inflammatory process of atherosclerosis." (PMID 35273600, 2022). "Sucnr1 might be a novel target for cutting off the transduction of succinate signal to prevent the inflammation of atherosclerosis." (PMID 35273600, 2022).
colitis (8 papers, 2018 to 2025). Inflammation of the colon. "In addition to a potential role modulating acute inflammation in colitis, the authors also demonstrated a direct role for SUCNR1 in intestinal fibrosis associated with CD." (PMID 30583500, 2018). "Studies on colitis have demonstrated that resting peritoneal macrophages from SUCNR1-deficient mice secrete less pro-inflammatory factors IL-1β, IL-6 and TNF-α and, thus, exert a protective effect against colitis." (PMID 40243444, 2025). "In the present study, we aimed to analyze the role of SUCNR1 in the priming step of the inflammasome activation in intestinal epithelial cells, and its relevance in colitis." (PMID 35327334, 2022). "The functional role of SUCNR1 in vivo was analyzed in a chronic murine model of colitis induced by DSS." (PMID 35327334, 2022). "The present study demonstrated, for the first time, that SUCNR1 mediated the inflammasome priming and the NFкB-pathway activation in both intestinal epithelial cells and a chronic murine model of colitis, suggesting a role for this receptor in Ulcerative Colitis." (PMID 35327334, 2022). "Importantly, SUCNR1-deficient mice were protected from acute inflammation and tissue damage in a 2,4,6-trinitrobenzene sulphonic acid (TNBS)-induced colitis model, which corresponded with a reduction in M1 macrophage markers in colonic tissue." (PMID 30583500, 2018). "Patients with UC and mice with DSS-induced colitis exhibit increased expression of SUCNR1, while SUCNR1-silenced mice show significantly greater resistance to DSS-induced colitis." (PMID 41030455, 2025). "Results demonstrated, for the first time, that SUCNR1 mediated NLRP3 priming in both intestinal epithelial cells and a murine model of DSS-colitis, and that this receptor correlated with inflammasome markers in human UC." (PMID 35327334, 2022). "On the other hand, mice lacking functional SUCNR1 are protected from acute inflammation in a colitis model, providing supportive evidence on the mediating role of the succinate-SUCNR1 axis in priming macrophages to the M1 state." (PMID 36605449, 2022). "Studies have shown that the upregulation and activation of SUCNR1 in intestinal macrophages increases the expression of proinflammatory cytokines and M1 macrophage marker genes, whereas a lack of SUCNR1 attenuates their expression, thereby protecting mice from colitis." (PMID 41476733, 2025).
lung carcinoma (8 papers, 2020 to 2025). "Succinate, an intermediate in the TCA cycle, has been highlighted for its role in TAM polarization and EMT induction in lung cancer through activation of the succinate receptor 1 (SUCNR1) and subsequent triggering of the PI3K/HIF-1α pathway." (PMID 39286635, 2024). "Subcutaneous implantation of lung cancer cells transfected with SUCNR-1 shRNA into a murine xenograft tumor model results in local tumor growth comparable to that from implantation of lung cancer cells transfected with control vector." (PMID 36344992, 2022). "Although a recent study showed that succinate enhanced the invasion and migration of lung cancer cells through SUCNR1, there is still little known about the role of SUCNR1 in oncogenesis." (PMID 33062639, 2020). "Recently, cancer-derived succinate was found to recruit monocytes, promote pro-tumorigenic TAM polarization and metastasis of human lung cancer through activation of succinate receptor (SUCNR1/GPR91) signaling." (PMID 33171762, 2020). "Furthermore, succinate activates p38 MAPK, Akt and AMPK in lung cancer cells, suggesting that succinate activates multiple signaling pathways via SUCNR-1 interaction." (PMID 36344992, 2022).
Arthritis (7 papers, 2018 to 2023). Inflammation of a joint. "using mice deficient for the succinate receptor Sucnr1/GPR91, attenuated arthritis development, and reduced traffic and expansion of Th17 cells to the lymph nodes, and conversely, succinate complementation enhanced recruitment and traffic of Th17 and arthritis severity." (PMID 37117227, 2023). "Researchers found that the genetic deficiency of Sucnr1, a succinate receptor expressed by immune cells, decreases trafficking of dendritic cells and reduces expansion of Th17 cells in the lymph nodes, reducing the symptoms of arthritis in the mouse antigen-induced arthritis model." (PMID 32235564, 2020). "In contrast, Sucnr1−/− mice were found to exhibit exacerbated allergic contact dermatitis and in this same study the authors also reported that SUCNR1 deficiency improved arthritis in the mouse model." (PMID 29520272, 2018).
liver fibrosis (7 papers, 2018 to 2025). "The cross-talk between steatotic hepatocytes and hepatic stellate cells through a unique succinate-SUCNR1 signaling pathway has been postulated to be the molecular basis for NASH-associated hepatic fibrosis." (PMID 34199098, 2021). "Other studies in the recent decade have affiliated the succinate-SUCNR1 axis to the pathogenesis of other fibrotic entities such as intestinal fibrosis and hepatic fibrosis." (PMID 40146935, 2025). "The succinate-Sucnr1 signaling pathway is also a key regulator of the molecular mechanisms driving liver fibrosis." (PMID 40238740, 2025). "The succinate–SUCNR-1 axis plays a pivotal role in liver fibrosis following hepatic damage." (PMID 37446354, 2023).
ischemia (6 papers, 2019 to 2025). A hypoperfusion of the BLOOD through an organ or tissue caused by a PATHOLOGIC CONSTRICTION or obstruction of its BLOOD VESSELS, or an absence of BLOOD CIRCULATION. "The present study shows that ischemia is associated with elevated SUCNR1 levels in the penumbra." (PMID 33806692, 2021). "One proposed mechanism involves succinate, a metabolite produced by the intestinal microbiota, which polarizes alveolar macrophages through the SUCNR1-dependent pathway, exacerbating ALI induced by intestinal ischemia-reperfusion." (PMID 39512354, 2024).
ovarian carcinoma (6 papers, 2020 to 2025). A malignant neoplasm originating from the surface ovarian epithelium. "Elevated levels of Succinate and the expression of Succinic acid receptor 1 (SUCNR1 or GPR91) have been associated with significant alterations in the immune cell functions in the ovarian cancer microenvironment." (PMID 40931345, 2025). "Investigators found an association between the expression of succinate receptor 1 (GPR91) and the phenotyping of ovarian cancer." (PMID 35205136, 2022). "SUCNR1 has been linked to altered immune infiltration of tumors in ovarian cancer and renal cancer." (PMID 40723216, 2025). "The expression of SUCNR1 was closely related to tumor infiltrating lymphocytes, multiple gene markers of immune cells, and T cell exhaustion in ovarian cancer." (PMID 33062639, 2020). "Together, this data suggests that dysregulated expression of SUCNR1 is related to the clinical outcome for ovarian cancer." (PMID 33062639, 2020). "The predictive value of SUCNR1 for prognosis in ovarian cancer was analyzed by the Kaplan-Meier plotter database." (PMID 33062639, 2020). "We found that MUC16 mutant ovarian cancer samples had higher SUCNR1 expression than MUC16 wild-type samples." (PMID 33062639, 2020). "Here, the genetic and expression profiles of SUCNR1 in ovarian cancer were analyzed using the cBioPortal, GEO and TIMER databases." (PMID 33062639, 2020). "Collectively, these results further indicate that SUCNR1 participates in the immune regulation of ovarian cancer." (PMID 33062639, 2020). "To further understand the molecular mechanism of SUCNR1 in ovarian cancer immunology, we performed a GSEA based on the Cancer Genome Atlas (TCGA) ovarian cancer RNAseq data." (PMID 33062639, 2020). "As SUCNR1 is amplified in ovarian cancer, we further analyzed the relationship between the amplification status of SUCNR1 and immune infiltration." (PMID 33062639, 2020). "Our analysis showed for the first time that SUCNR1 was correlated with immune cell infiltration in ovarian cancer." (PMID 33062639, 2020). "We draw our conclusions through correlation analysis based on several public databases, and did not conduct in vivo experiments to confirm the immunoregulatory role of SUCNR1 in ovarian cancer." (PMID 33062639, 2020). "In the current study, we reported that SUCNR1 was amplified and predicted a poor prognosis in ovarian cancer." (PMID 33062639, 2020). "Kaplan-Meier Plotter was used to assess the prognostic value of SUCNR1 in patients with ovarian cancer." (PMID 33062639, 2020). "In the current study, we explored the potential role and clinical significance of SUCNR1 in ovarian cancer from multiple databases." (PMID 33062639, 2020). "We assessed the expression of SUCNR1 between ovarian cancer and normal tissues by using the GEO database." (PMID 33062639, 2020). "We also performed Gene Set Enrichment Analysis (GSEA) to reveal biological function of SUCNR1 in ovarian cancer." (PMID 33062639, 2020). "The Oncomine database demonstrated that the copy number of SUCNR1 was significantly elevated in ovarian cancer than in normal blood and ovary samples." (PMID 33062639, 2020). "According to cBioPortal, SUCNR1 showed a higher percentage of amplification in several cancer types, including ovarian cancer." (PMID 33062639, 2020). "In addition, we found that SUCNR1 was amplified in ovarian cancer, and the high expression of SUCNR1 predicted worse progression-free survival (p = 0.0073, HR = 1.49, 95% CI = 1.11–2)." (PMID 33062639, 2020). "SUCNR1 was the most relevant factor for the immunoreactive phenotype of ovarian cancer." (PMID 33062639, 2020). "The biological roles of SUCNR1 in ovarian cancer were identified by GSEA." (PMID 33062639, 2020). "Furthermore, SUCNR1 has also been identified as a poor prognostic factor in patients with ovarian cancer." (PMID 33062639, 2020). "Together, this data strongly suggests that SUCNR1 may function as an immune infiltration regulator in ovarian cancer." (PMID 33062639, 2020).
ovarian carcinoma (continued). "The prognostic value of SUCNR1 was also demonstrated in patients with ovarian cancer." (PMID 33062639, 2020). "We observed the association of SUCNR1 expression with interleukins, including IL1B (cor = 0.473, p = 2.86e-18), IL7 (cor = 0.39, p = 1.78e-12), IL16 (cor = 0.508, p = 2.66e-21), and IL18 (cor = 0.348, p = 4.67e-10), in ovarian cancer." (PMID 33062639, 2020). "In addition, a high expression of SUCNR1 was positively correlated with various immune-related functional biological processes of ovarian cancer mapping in KEGG pathway, Reactome pathway, Wikipathway, and Panther pathway." (PMID 33062639, 2020). "Our results indicate that SUCNR1 were amplified and upregulated in ovarian cancer." (PMID 33062639, 2020). "We evaluated the clinical implication of SUCNR1 in ovarian cancer." (PMID 33062639, 2020). "This indicates that SUCNR1 has an immunoregulatory role in ovarian cancer." (PMID 33062639, 2020). "Additionally, SUCNR1 was reported with the worst progression-free survival in ovarian cancer." (PMID 36551549, 2022). "Besides, MHC molecules, including HLA-B (cor = 0.365, p = 5.69e-11), HLA-DMA (cor = 0.413, p = 7.02e-14), HLA-DPA1 (cor = 0.475, p = 2.03e-18), HLA-DQA1 (cor = 0.467, p = 8.07e-18), and HLA-E (cor = 0.447, p = 2.6e-16), were significantly correlated with the expression of SUCNR1 in ovarian cancer." (PMID 33062639, 2020). "However, the clinical significance of SUCNR1 in ovarian cancer and its correlation with tumor-infiltrating lymphocytes remain unclear." (PMID 33062639, 2020). "Therefore, our study highlights the immunoregulatory role of SUCNR1 in ovarian cancer." (PMID 33062639, 2020).
diabetic retinopathy (5 papers, 2019 to 2024). "Collectively, these findings underline the critical involvement of succinate and SUCNR1 in the pathogenesis of diabetic retinopathy, suggesting new potential therapeutic targets." (PMID 38182909, 2024). "Recent investigations, however, also implicate succinate and SUCNR1 in the progression of diabetic retinopathy, particularly in retinal vascular dysfunction and neurodegeneration." (PMID 38182909, 2024). "Diabetic retinopathy is intricately tied to SUCNR1; this receptor is found in key areas of the retina, such as the retinal ganglion cell layer and the retinal pigment epithelium." (PMID 38182909, 2024).
Glucose intolerance (4 papers, 2017 to 2024). Glucose intolerance (GI) can be defined as dysglycemia that comprises both prediabetes and diabetes. "While the human study offers valuable associative insights, the concurrent presence of heightened glucose intolerance, insulin secretion, and succinate response in prediabetic conditions prevents us from conclusively establishing a direct link between the succinate/SUCNR1 axis and insulin secretion." (PMID 38713514, 2024). "Consistent with this hypothesis, we show that β cell–specific depletion of SUCNR1 in mice leads to an aberrant metabolic phenotype characterized by increased glucose intolerance and defects in insulin secretion under HFD feeding." (PMID 38713514, 2024). "Moreover, our findings align with an earlier study using global-Sucnr1-knockout mice, which exhibited progressive glucose intolerance under HFD and an impaired insulin response, occurring as part of a complex phenotype." (PMID 38713514, 2024). "Specific β cell ablation of SUCNR1 induces glucose intolerance due to β cell impairment." (PMID 38713514, 2024). "After 8 weeks of HFD feeding, glucose intolerance developed in HFD-fed WT animals, while Sucnr1−/− mice tended to remain glucose tolerant." (PMID 28382382, 2017). "Notably, global-Sucnr1-knockout mice fed a high-fat diet (HFD) show defective insulin secretion and glucose intolerance, without significant changes in β cell mass, raising suspicion of its role as a regulator of β cell function." (PMID 38713514, 2024).